FADD (Fas associated via death domain)
Diseases named in the same sentence as FADD in open-access papers (continued):
Sharing a sentence is not in itself a finding about the gene and the disease.
lymph node metastasis (13 papers, 2006 to 2022). "High FADD expression was associated with an increased rate of lymph node metastasis of HNCs and with a shorter distant metastasis-free interval when lymph node metastases were present." (PMID 33810241, 2021). "N status: A significant association was found among FADD alterations and positive-lymph node metastasis (odds ratio [OR] = 2.07, 95% CI = 1.47–2.91, p < 0.001), although a certain degree of heterogeneity was found (p = 0.008, I2 = 55.2)." (PMID 32847023, 2020). "We performed a 120-months survival analysis and found that FADD expression was associated with lymph node metastasis." (PMID 31443698, 2019). "In the current study of male HNSCC patients, we showed that FADD amplification was present in 69 of 339 cases (20.4%), and gene amplification was associated with a higher incidence of lymph node metastasis (LNM) and extracapsular spread (ECS)." (PMID 27764170, 2016). "In conclusion, our data reveal that FADD gene copy number and protein expression can be considered potential prognostic markers and are closely associated with lymph node metastasis in patients with OSCC in Taiwan." (PMID 27764170, 2016). "Both FADD gene copy number amplification and high protein expression were significantly associated with lymph node metastasis (P < 0.001)." (PMID 27764170, 2016). "High FADD protein expression was also associated with young age at diagnosis (P = 0.029) and lymph node metastasis (P = 0.025) in this subgroup." (PMID 27764170, 2016). "Both FADD gene amplification and protein overexpression were associated with lymph node metastasis and perineural invasion." (PMID 27764170, 2016). "In addition to lymph node metastasis, high expression of FADD was significantly associated with young age at diagnosis and poorer tumor differentiation." (PMID 27764170, 2016). "Similarly to FADD amplification, high FADD protein expression is also significantly associated with lymph node metastasis (P < 0.001)." (PMID 27764170, 2016). "FADD is an important gene that is associated with lymph node metastasis and prognosis in OSCC." (PMID 27764170, 2016). "FasL and FADD also showed modest correlations with one or more cancer risk factors, but none of the markers was significantly associated with either tumor stage or lymph node metastasis, the only two clinical factors that predicted survival in these ESCC cases." (PMID 19728877, 2009). "Additional in vitro studies have similarly observed increased FADD expression in OSCC, with FADD upregulation in a Taiwanese cohort being associated with increased risks of lymph node metastasis and poorer overall prognosis." (PMID 35163485, 2022). "This is also true for HNCs with lymph node metastasis that possess high FADD expression alone or in combination with high DR5 or caspase-8 expression." (PMID 33810241, 2021). "An increase in FADD expression was shown to be associated with a higher incidence of lymph node metastasis at presentation and with a shorter DMFI when lymph node metastases are present." (PMID 31443698, 2019). "The relationship between high FADD protein expression and lymph node metastasis in head and neck cancer has been demonstrated in several studies." (PMID 27764170, 2016). "In a different cohort, where FADD immunohistochemistry staining was performed in 100 samples of HNSCC tissues, a significant increase in FADD expression in primary tumors was associated with lymph node metastasis and worse disease-free and overall survival." (PMID 33737574, 2021). "However, FADD expression was positively correlated with a younger age at diagnosis (P = 0.049) and lymph node metastasis (P = 0.003)." (PMID 31443698, 2019). "In addition to FADD, primary tumor status (HR = 1.676, 95% CI, 1.256–2.238) and lymph node metastasis (HR = 1.931, 95% CI, 1.310–2.846) were significantly associated with a poorer OS." (PMID 27764170, 2016).
lymph node metastasis (continued). "Furthermore, expression of cortactin, cyclin D1 and more recently FADD, have been described separately as potential predictors for increased disease-related mortality, for lymph node metastasis and poor prognosis." (PMID 18268491, 2008). "High FADD expression has been identified frequently in HNSCC (>30%) and is related to a higher incidence of lymph node metastasis and shorter distant metastasis-free internal." (PMID 33456497, 2020). "Tumors with lymph node metastasis and lymph node extra-capsular spread (ECS) had a significantly higher frequency of FADD amplification (P ≤ 0.001)." (PMID 27764170, 2016). "Since lymph node metastases have been shown to be an important prognostic factor for DSM, we assessed the additional prognostic value of cyclin D1, FADD and cortactin in late stage LSCC." (PMID 18268491, 2008). "Secondly, we evaluated whether protein expression of FADD, cyclin D1 and cortactin were related to increased DSM and lymph node metastasis." (PMID 18268491, 2008). "FADD protein expression was independent of lymph node metastasis and patients with both high FADD protein expression and lymph node metastasis had the worst prognosis for survival." (PMID 18268491, 2008). "Lower FADD expression was significantly associated with better disease-free survival and overall survival in HNC patients with lymph node metastasis, although FADD expression did not significantly affect the survival of HNC patients without lymph node metastasis." (PMID 33810241, 2021). "A previous study revealed that patients with lymph node metastasis (LNM) in head and neck squamous cell carcinoma showed higher FADD expression than those without LNM." (PMID 33194633, 2020). "We show that both cortactin and lymph node metastasis are good predictors for DSM using a multivariate model independent of cyclin D1 and FADD." (PMID 18268491, 2008).
melanoma (13 papers, 2013 to 2024). A malignant, usually aggressive tumor composed of atypical, neoplastic melanocytes. "Curcumin treatment of melanoma cells caused caspase-8 activation of the death receptor Fas-initiated Fas-Associated protein with Death Domain (FADD) apoptotic pathway." (PMID 37803407, 2023). "H2S also facilitated melanoma cell apoptosis and inhibited tumor growth by upregulating Fas-associated protein with a novel death domain (FADD)." (PMID 35774378, 2022). "FADD deficiency inhibited FAK expression by promoting miR-7a in two murine melanoma cells with the same origin and genetic background but different metastatic potency, B16F10 and B16F1." (PMID 27286445, 2016). "Previous studies from our group have demonstrated that combination treatment with bortezomib and IFN-α synergistically enhances melanoma apoptotic cell death through the Fas Associated Death Domain (FADD)-induced caspase-8 activation." (PMID 27783987, 2016). "Overexpression of FADD or its variant N-FADD self-initiates apoptosis of B16F10 melanoma cells by activating caspases dependent cell death in vitro." (PMID 27767039, 2016). "In our experiment, immunofluorescence and its quantitative results showed transfection of FADD or N-FADD caused apoptosis of B16F10 melanoma cells by activating pro-caspase-3." (PMID 27767039, 2016). "In summary, our study shows, for the first time, that the slow-releasing H2S donor ADT-OH is a potential antitumour agent because it enhances the FADD-dependent extrinsic apoptosis of melanoma cells." (PMID 31949127, 2020). "In dissecting the role of FADD in the treatment of melanoma with ADT-OH, we performed additional experiments using FADD-knockout B16F10 cell lines." (PMID 31949127, 2020). "Based on these findings, we evaluated the combined effects of ADT-OH treatment and FADD overexpression on melanoma cell death in vivo using a mouse xenograft model." (PMID 31949127, 2020). "Since ADT-OH treatment combined with overexpression of FADD induced apparent apoptosis of melanoma cells in vitro, we further explored their combined effects on melanoma cell apoptosis in vivo." (PMID 31949127, 2020). "The data showed that the FADD-KO melanoma cells had little response to ADT-OH and that the level of apoptosis induced by ADT-OH was much lower than that of the wild-type cells." (PMID 31949127, 2020). "Next, to further demonstrate the role of FADD in the treatment of melanoma in vivo with ADT-OH, we constructed a mouse melanoma model by subcutaneously injecting B16F10 cells or B16F10 FADD-KO cells into C57BL/6 mice." (PMID 31949127, 2020). "ADT-OH treatment combined with overexpression of FADD significantly induced apoptosis and suppressed the growth of melanoma cells both in vitro and in vivo, providing a potential effective strategy for melanoma therapy." (PMID 31949127, 2020). "The melanomas derived from the FADD-knockout cells stably grew to 3000 mm3 within 14 d, and there was no significant change in tumour size after ADT-OH treatment." (PMID 31949127, 2020). "Our group has previously shown a similar pattern of caspase activation and cleavage of PARP with bortezomib in human melanoma cell lines which demonstrated bortezomib-induced apoptosis as a result of FADD-induced caspase-8 activation." (PMID 27783987, 2016). "The FADD/miR-7a/FAK pathway acted as a regulatory pathway of migration in murine melanoma cells, and this finding was consolidated by an in vivo mouse metastatic model." (PMID 27286445, 2016). "Over expression of FADD or N-FADD evoked the B16F10 melanoma cells apoptosis significantly compared with empty vector pcDNA3.1 (−)." (PMID 27767039, 2016). "Since both miR-7a and FAK were reported to be involved in cell migration in melanoma, and our previous study demonstrated FADD's correlations with the two of them." (PMID 27286445, 2016).
melanoma (continued). "This study illustrates a potential role of FADD in murine melanoma cell migration by regulating FAK expression; a pathway that involves miR-7a as a crucial mediator." (PMID 27286445, 2016). "Taken together, our data provide a novel explanation regarding how FADD regulates cell migration in murine melanoma cells." (PMID 27286445, 2016). "Detailed mechanism involving FADD/miR-7a/FAK in these two melanoma cells still remains exclusive and requires further investigation." (PMID 27286445, 2016). "The highly metastatic melanoma cell line B16F10 expresses high basic levels of FADD and FAK, low basic levels of miR-7a." (PMID 27286445, 2016). "In conclusion, we provide a new model of regulation of cell migration by the FADD-miR-7a-FAK pathway in murine melanoma cells." (PMID 27286445, 2016). "Here, we determined whether overexpression of mouse FADD or the combination of mouse FADD overexpression with ADT-OH treatment in B16F10 melanoma cells induces more apoptosis." (PMID 31949127, 2020). "Firstly, we checked whether over-expression of mouse FADD and its truncated variant N-FADD (m-FADD, 1–181 aa) in B16F10 melanoma cells could induce the apoptosis of the cells." (PMID 27767039, 2016). "However, the mechanisms between FADD and tumor metastasis or cell migration are still unclear, especially in melanoma." (PMID 27286445, 2016). "Therefore it was reasonable to assume that FADD could have impact on cell migration via miR-7a targeting FAK signaling pathway in murine melanoma cells." (PMID 27286445, 2016). "Altogether, these results show that FADD knockout greatly blunts the pro-apoptotic effect of ADT-OH and indicate that FADD plays an important role in the treatment of melanoma with ADT-OH." (PMID 31949127, 2020). "Here, our study showed that ADT-OH significantly increased the protein level of FADD in several cancer cell lines, including B16F10 melanoma cells." (PMID 31949127, 2020). "We also investigated the relationship between FADD and FAK expression in two murine melanoma cell lines, B16F10 and B16F1, and obtained consistent results with MEFs." (PMID 27286445, 2016). "Firstly, we measured the basic expression of FADD, FAK and miR-7a in these two murine melanoma cells." (PMID 27286445, 2016). "Here we raised the question regarding the correlation between expression of FADD and FAK in melanoma." (PMID 27286445, 2016). "According to an online cancer transcriptome database Oncomine, FADD and FAK are both over-expressed in human melanoma." (PMID 27286445, 2016). "In addition, in vivo experiments showed that ADT-OH had no significant therapeutic effect on FADD-knockout melanoma cells." (PMID 31949127, 2020). "FADD levels were not affected significantly by Solamargine treatment in any melanoma cell line." (PMID 26889092, 2016). "Here, we present a new finding that FADD could regulate the expression of FAK, a non-receptor protein tyrosine kinase overexpressed in many cancers, and played an important role in cell migration in murine MEF and melanoma cells with different metastatic potential, B16F10 and B16F1." (PMID 27286445, 2016).
prostate carcinoma (13 papers, 2006 to 2025). A carcinoma that arises from epithelial cells of the prostate gland. "In general, a decreased expression of FADD was noted in conditions such as acute myeloid leukemia, thymic lymphoma, glioblastoma, pancreatic cancer, colorectal cancer, renal cancer, and prostate cancer." (PMID 38542202, 2024). "Previous studies have demonstrated the phosphorylation of FADD and its impact on anticancer drug efficacy in human prostate cancer cells." (PMID 38542202, 2024). "Further multivariate Cox regression analysis was performed to select 6-gene prognostic signature (FADD, GABARAPL2, MYC, RAB24, RUBCN, and NPC1) and calculated the risk score of the prostate cancer patients." (PMID 33402116, 2021). "FADD phosphorylation has been analyzed in numerous solid tumors, for example in prostate cancer cells, where a reduction of FADD phosphorylation has been reported." (PMID 27556297, 2016). "Studies have demonstrated that phosphorylation of FADD at Ser194 can be induced by paclitaxel in human prostate cancer cells leading to cell cycle arrest and apoptosis." (PMID 23285096, 2012). "Although the role of p-FADD in ESCC outcome is unclear, higher levels of p-FADD protein correlated with reduced survival in patients with lung adenocarcinomas and prostate cancer." (PMID 19728877, 2009). "We recently indicated an important role for JNK upstream of FADD phosphorylation at 194 serine on paclitaxel-induced apoptosis in human prostate cancer cells." (PMID 16450001, 2006). "Since we previously demonstrated activation of JNK and phosphorylation of FADD by paclitaxel in prostate cancer cells, we examined the cytotoxicity of paclitaxel for long-term tamoxifen treatment, in MDA-MB-231." (PMID 16450001, 2006). "that MAP2K1 phosphorylates FADD in prostate cancer—was also reported in an independent study." (PMID 27078000, 2016). "Recently, we have shown that FADD phosphorylation at Ser194 can be induced by paclitaxel, with impact on functions both upstream and downstream of the MEKK1/MKK7/JNK1 pathway, closely associated with sensitisation to chemotherapy in prostate cancer cells." (PMID 16450001, 2006). "In prostate cancer, HIPK3-mediated FADD phosphorylation is crucial for FAS-induced apoptosis." (PMID 40280416, 2025). "Our results give support to this hypothesis as they showed an increased expression of FADD and CASP 8 genes in both breast and prostate cancer cell lines and for the prostate cell lines also of FAS gene, associated with the external apoptosis pathway." (PMID 29444163, 2018). "More specifically, it has been reported that PKCζ does not phosphorylate FADD in DU145 prostate cancer cells." (PMID 27556297, 2016). "Induction of p-FADD results in suppression of cancer cell growth and invasion through reduction in the non-phosphorylated form in prostate cancer." (PMID 19728877, 2009). "Consequently, we try to demonstrate here 3-azidoWA as well as TRAIL mediated inhibition of MMP-2 in cervical (data not shown) and prostate cancer cell line through induction of extracellular Par-4 which has been shown to induce extrinsic apoptotic pathway by FADD-caspase-8-caspase-3 activation." (PMID 22962598, 2012). "Interestingly, this non-apoptotic form of cell death occurred in normal but not in prostate cancer epithelial cells, indicating that this alternative pathway initiated by FADD may be disrupted in some cancer cells." (PMID 21049020, 2010).
viral infection (13 papers, 2014 to 2025). "FADD is of particular interest as it encodes for a protein that interfaces with cell surface receptors to mediate cell apoptotic signals that can help mitigate viral infections by disrupting mammalian cell replication." (PMID 30208883, 2018). "Apart from its critical role in death receptor signaling of apoptosis, FADD has emerged as a new actor in cancer development, inflammation, innate immunity, and virus infection." (PMID 38650851, 2024). "Our results reveal that even a low viral infection dose is sufficient to kill all Ripk3−/−Fadd−/− DKO mice shortly after infection even to a higher extend than Ripk3−/− mice, showing indicating that FADD-mediated apoptosis is implicated." (PMID 33976111, 2021). "FADD and RIP1 are crucial for signaling against viruses, since cells lacking FADD and RIP1 were defective in production of type I IFNs and were more susceptible to viral infection." (PMID 33498715, 2021). "Neither virus infection exhibited any association of FADD with full-length (55kDa) cFLIP (also known as cFLIPLong or cFLIPL)." (PMID 33126536, 2020). "Since we showed that both cFLIP and FADD were capable of improving cellular immune responses to SIVmac Gag and HIVBal gp140, we asked whether they could influence virus infection in vivo." (PMID 25807052, 2015). "In this regard, the greater association of MAVS with c-FLIPL than with c-FLIPS during viral infection may profoundly affect not only the ability of RIG-I, FADD, and RIP1 to translocate to MAVS at the mitochondria, but c-FLIPL may also inhibit cleavage of MAVS by the CVB3 3Cpro protease." (PMID 24816846, 2014). "Several immune related DEGs (FADD, MAPK15, and GUCY1A2) in Fayoumi at 2 dpi, had been previously identified to be important in the host response to viral infection and the inflammatory response in cell lines." (PMID 30208883, 2018). "We found that necroptosis increased from 1.58% in wildtype to 5.20% in FADD-/- HIV-1-infected Jurkat cells, albeit the kinetics of viral infection was the same in both cell lines." (PMID 24714696, 2014).